TRPA1 (transient receptor potential cation channel subfamily A member 1)
Diseases named in the same sentence as TRPA1 in open-access papers (continued):
Sharing a sentence is not in itself a finding about the gene and the disease.
cancer (continued). "Since TRPA1 channels have been shown to be important in the transduction of pain in cancer, evaluations of these antagonists in pain cancer models would be valuable." (PMID 35053150, 2021). "Several studies have reported the role of TRPA1 in mechanical sensory stimulation, particularly in harmful mechanotransduction due to nerve damage, cancer treatment, and inflammation." (PMID 35053150, 2021). "An analysis of data from The Cancer Genome Atlas project shows that high expression of the TRPA1 gene correlates with improved survival in liver, intrahepatic bile duct and bladder cancers." (PMID 33479347, 2021). "Extending these findings to sensitivity to cancer therapies, TRPA1 was found to promote resistance to the traditional, platinum-based chemotherapeutic carboplatin through a mechanism dependent on the Ca2+-dependent anti-apoptotic mechanism." (PMID 31434226, 2019). "TRPA1 promotes an increase in Ca2+ influx in response to ROS generation which results in elevated expression of the anti-apoptotic protein Mcl-1 and cancer cell survival." (PMID 31434226, 2019). "Oxidation of thiol redox system and cysteine groups in cancer cells have the main role in the activation of thiol group containing TRP channels such as TRPA1, TRPM8 and TRPV1." (PMID 30858386, 2019). "Mutational analyses in both mice and flies demonstrates that this effect of vinca alkaloids requires TrpA1 revealing an ancient and conserved molecular mechanism of these anti-cancer drugs on sensory function." (PMID 29084244, 2017). "Evidently, in the presence of exosomes, TRPA1 in cancer cells was depleted indicating that astrocytes are indeed acting on HCC-515 cells via an exosome-mediated mechanism." (PMID 29038531, 2017). "On one hand, the overexpression of the transient receptor potential ankyrin 1 (TRPA1) in the DRG itself mediates molecular responses to cancer development and transduces cold stimuli to the nociceptor sensory neurons." (PMID 30510606, 2017). "Also, IL6 positively correlates with TRPA1 in many cancers but negatively in kidney renal papillary cell carcinoma (KIRP)." (PMID 39770499, 2024). "However, every cancer type has a different expression and modulation of TRPA1, with the most common trait being the hypermethylation of the gene promoter." (PMID 39770499, 2024). "Many studies on the connection between TRPA1 and oxidative stress were performed in cancer." (PMID 39064963, 2024). "TRPA1 plays an important role in regulating cancer cells’ response to oxidative stress, which contains some elements that may be applied for other than cancer pathologies." (PMID 39064963, 2024). "Emerging evidence suggests that TRPA1 may have significant implications for the occurrence and development of cancer." (PMID 38430394, 2024). "Numerous works demonstrate that TRPA1 is upregulated in several cancer types." (PMID 39064963, 2024). "Many papers suggest that TRPM8, TRPV6, or TRPA1 could be either markers of PDAC or specific targets for cancer therapies based on their localization in the cell membrane, making them easily druggable." (PMID 38543130, 2024). "TRPA1 also participates in the migration and proliferation of some cancer cells." (PMID 39770499, 2024). "In summary, TRPA1 expression is modulated in many cancers and may play an essential role in the development of many malignancies, with implications for patient outcomes." (PMID 39770499, 2024). "This study offers an overview of TRPA1 gene expression and methylation and its relation to overall survival, cancer stages and metastasis, tumour purity and immune infiltration using a pan-cancer analysis of several databases." (PMID 39770499, 2024). "NCS-1 is a calcium (Ca2+) sensor found in many tissues, primarily neurons, and TRPA1 is a Ca2+ channel involved not only in thermal and pain sensation but also in conditions such as cancer and chemotherapy-induced peripheral neuropathy, in which NCS-1 is also a regulatory component." (PMID 38564162, 2024).
cancer (continued). "TRPA1 activation in lung epithelial cancer cells (A549) can induce a decrease in cell invasion by inhibiting the cyclooxygenase-2 (COX-2)/prostaglandin E2 pathway in hypoxic cancer cells in vitro." (PMID 37892239, 2023). "TRPA1 channels are widely distributed in the intestinal tract and other tissues, and may play a key role in various cancers." (PMID 36641489, 2023). "TRPA1 is emerging as the primary redox-sensitive TRP isoform in cancer microenvironment." (PMID 37393347, 2023). "In Section 5, we focus on the pharmacology of TRPA1 channels and describe how stimulating or inhibiting TRPA1 activity could represent a novel therapeutic strategy to induce ROS-dependent cancer cell death." (PMID 37174661, 2023). "In addition, TRPA1-mediated depolarization of peripheral nociceptors is involved in cancer-induced bone pain and cancer-related neuropathic pain." (PMID 37174661, 2023). "Therefore, a variety of agonists are potentially available to stimulate TRPA1 and enhance ROS-dependent apoptosis in cancer cell types that succumb in response to sustained Ca2+ entry via TRPA1." (PMID 37174661, 2023). "Nevertheless, parallel investigations provided evidence that the TRPA1-dependent increase in [Ca2+]i may also support H2O2-induced apoptosis in other types of cancer cells." (PMID 37174661, 2023). "Furthermore, TRPA1 has also been detected in acidic lysosomal vesicles, which represent an emerging pro-oncogenic Ca2+ releasing organelle in cancer cells and stimulate InsP3-dependent ER Ca2+ spikes via CICR." (PMID 37174661, 2023). "The role of TRPA1 in sustaining chronic cancer pain in rodent models is supported by robust data." (PMID 37892239, 2023). "A recent series of studies showed that TRPA1 may also serve as a crucial sensor of redox signaling in cancer cells and that extracellular Ca2+ entry through TRPA1 can promote either cell survival or cell death in response to oxidative stress." (PMID 37174661, 2023). "Therefore, TRPA1 can contribute to tumorigenesis, although its effect can vary depending on the cancer type, e.g., TRPA1-mediated Ca2+ signals stimulate and inhibit migration in PTECs and PDACs, respectively." (PMID 37174661, 2023). "Antagonism of TRPA1 produces an antinociceptive effect in rodent models of cancer pain." (PMID 36098890, 2023). "To date, there are only two clinical trials for TRPA1 related to cancer." (PMID 37892239, 2023). "In most cancer samples, particularly in the poorly differentiated cases, TRPA1 immunopositivity was substantially stronger in the epithelial, vascular endothelial and some lymphoid cells, but the staining was mainly located in the nuclei, clearly suggesting a non-specific reaction." (PMID 35163843, 2022). "TRPA1 decreases ROS accumulation in cancer cells and thus promotes cell survival." (PMID 36110953, 2022). "TRPA1 can be activated in neurons and cancer cells through different stimuli." (PMID 35982414, 2022). "TRPA1 is activated by reactive oxygen species (ROS), naturally, TRPA1 could be exploited for targeted ROS-related cancer therapies." (PMID 36499622, 2022). "Altogether, these results and their role in cancer suggest that TRPA1 activation by acidic pHe and hypoxia may play a significant role in promoting cancer progression, highlighting its potential as a therapeutic target." (PMID 35806388, 2022). "The role of TRPA1 as a ROS sensor has been demonstrated also in cancer cells." (PMID 35806388, 2022). "TRPA1 can be activated in neurons and cancer cells by various stimuli, including ROS." (PMID 35982414, 2022). "The expression of TRP channels, such as transient receptor potential vanilloid 1 (TRPV1) and transient receptor potential ankyrin 1 (TRPA1), in cells involved in detecting cancer pain and their role in pain-sensing makes them potential targets for pain relief compounds." (PMID 35053150, 2021).
cancer (continued). "A possible unknown role of TRPA1 that may contribute to the pathogenesis of cancer and other inflammatory diseases is its role in modulating the metabolism of CD8+ T cells." (PMID 34041030, 2021). "Similarly, TRPA1 protein was reportedly detected by NB110-40763 antibody in the cancer cell line A54925." (PMID 31811235, 2019). "Finally, we evaluated a therapeutic strategy for the relief of this perineural cancer pain by blocking the TRPA1 channel." (PMID 30510606, 2017). "We hypothesized that such intercellular communication could be responsible for the downregulation of TRPA1 observed in the cancer cells invading the brain." (PMID 29038531, 2017). "The direct activation of TrpA1 channels could occur via binding of anti-cancer drugs to previously identified TrpA1 protein domains." (PMID 29084244, 2017). "Furthermore, we show that upon metastasis to the brain, TRPA1 gets depleted, an effect triggered by the transfer of TRPA1-targeting exosomal microRNA (miRNA-142-3p) from brain astrocytes to cancer cells." (PMID 29038531, 2017). "Our analyses in mice and flies demonstrate that the effects of vinca alkaloids on sensory neuron function and pain hypersensitivity are conserved evolutionarily across diverse phyla, revealing an ancient and conserved role for the TrpA1 channel in the cellular response to anti-cancer drugs." (PMID 29084244, 2017). "Several reports implicate TRPV1 and TRPA1 in cancer pain, although there is a large gap in knowledge since the mechanisms for tumor-induced activation of these TRP receptors are unknown." (PMID 26007300, 2015). "Chemotherapeutic agents like cyclophosphamide and ifosfamide for cancer, severe arthritis, multiple sclerosis, and lupus generate acrolein as a metabolite, suggesting that TRPA1 may be involved in the side effects of such conditions." (PMID 19305786, 2008). "Finally, TRPV4 is co-expressed with different TRP channels (TRPV1 and TRPA1), and the blockage of these receptors may also reduce cancer-induced nociception." (PMID 38730655, 2024). "Therefore, TRPA1 may play multiple important roles in the connection between oxidative stress and cancer transformation, illustrating its general role as an oxidative stress sensor and modulator." (PMID 39064963, 2024). "Therefore, the cancer microenvironment has been recognized as the ideal milieu to activate TRPA1." (PMID 37174661, 2023). "Moreover, activation of TRPA1 in cancer pain models increases production of hydrogen peroxide (H2O2), which maintains TRPA1 activation/sensitization and these H2O2 levels may be caused by an augmented activity of NADPH oxidase and superoxide dismutase as well." (PMID 36098890, 2023). "In this review, we will describe some possible mechanisms involved in the nociception process associated with cancer that are mediated by factors produced by the TM and which could play an essential role in the direct activation or sensitization of the TRPV1 and TRPA1 channels." (PMID 35053150, 2021). "TRPA1 activation is associated with a non-canonical oxidative-stress defense, as well as a canonical ROS-neutralizing mechanism, thus upregulating anti-apoptotic pathways that favor cancer progression." (PMID 34831352, 2021). "However, there are few reports on whether TRPA1 is involved in regulating the complexity of cancer pain and the occurrence and development of temperature sensitivity; thus, further research is required." (PMID 35295475, 2021). "The PLC, PI3K, and MAPK-ERK signaling pathways, activate downstream kinases, such as PKC and PKA, which phosphorylate TRPV1 and TRPA1 channels and promote channel sensitization and reduction of their activation threshold, potentially contributing to the pain sensation experienced by cancer patients." (PMID 35053150, 2021).
cancer (continued). "Furthermore, high concentrations of H2O2 (50 μM), which are in the same range that has been reported in the cancer microenvironment, also evoked a sustained increase in [Ca2+]i in mCRC cells that was sensitive to the removal of extracellular Ca2+ and the abrogation of TRPA1 signaling." (PMID 40813985, 2025). "In the following subsections, we will examine the role of TRPML1, TRPA1, TRPM2 and TRPV1 in cancer processes mediated by oxidative stress in different tumor types." (PMID 40813985, 2025). "Recent studies suggest that the main channels involved in the oxidative stress-mediated cancer process are TRPML1, TRPA1, TRPM2 and TRPV1." (PMID 40813985, 2025). "Taking these data together shows that the effect of TRPA1 and TRPV1 activation greatly depends on the cancer cell types and complex sensory–vascular–immune–tumor interactions in the cancer microenvironment." (PMID 38612571, 2024). "Administration of SC144, a complexed IL-6R-gp130 inhibitor, alleviated mechanical and thermal hypersensitivity in BCP rats, reversing the upregulation of TRPA1, p-p38-MAPK, p-JNK, and PI3K-mTOR induced by cancer." (PMID 38940936, 2024). "The binding of TRPA1 and FGFR2 increases the activation of MAPK/ERK and PLC-γ1 pathways, leading to the proliferation and invasion of cancer cells." (PMID 39408656, 2024). "Although many studies have already addressed the role of other TRP channels, including TRPA1 and TRPV1, in the process of cancer pain development, our review mainly focused on TRPV4’s action, addressing the uniqueness of this protein." (PMID 38730655, 2024). "Recent drug discovery studies revealed the TRPA1 and TRPV1 channels to be potential therapeutic targets in many diseases including asthma, pain, neuro-psychiatric disorders, and different types of cancers." (PMID 38612571, 2024). "The reduction in TRPA1 levels stops the activation of the fibroblast growth factor receptor 2 (FGFR2), preventing the spread of cancer cells to the brain." (PMID 39408656, 2024). "Our results show, for the first time in PDAC, that 4-HNE, within the concentration range found in cancer patients, rapidly activates Ca2+ uptake in PDAC cells, as previously demonstrated in transfected HEK 293 cells expressing rat TRPA1 cDNA." (PMID 38543130, 2024). "The results presented so far sustain the role of TRPA1 and TRPV1 in cancer cell proliferation but are irrelevant to the modulation of channels by ROS." (PMID 37507867, 2023). "Based on the evidence that TRPA1 presents a high redox-sensing capability and that intracellular Ca2+ signaling finely tunes tumorigenesis, recent investigations sought to unravel whether and how TRPA1 confers cancer cells the ability to cope with or succumb to oxidative stress." (PMID 37174661, 2023). "Finally, we discuss how the redox-sensing capability of TRPA1 could be used by certain cancer cells to engage a non-canonical antioxidant defense program, while ROS-dependent TRPA1 activation leads to intracellular Ca2+ overload, mitochondrial dysfunction, and apoptosis in other cancer types." (PMID 37174661, 2023). "Among the Transient Receptor Potential (TRP) family, several channels, such as TRP Ankyrin 1 (TRPA1) and Vanilloid 1 (TRPV1), have been suggested to play roles in many cancer types, including breast, digestive, gliomas, lung, prostate and HNSCC." (PMID 35163843, 2022). "TRPA1 interaction with fibroblast growth factor receptor 2 (FGFR2) induces the activation of the receptor, promoting cancer cells’ proliferation and invasion, prompting lung adenocarcinoma metastasisation to the brain." (PMID 35806388, 2022). "The tissue enhanced TRPA1 (intestine, urinary bladder, and vagina) and group-enriched TRPM3 (brain, kidney, and retina) also exhibited perturbed expression in corresponding cancer types." (PMID 35614079, 2022). "TRPA1 and TRPC5 perform an important role in transducing chemical nociceptive stimuli, but upregulated TRPA1 and TRPC5 reveal poor prognosis in cancers." (PMID 36045706, 2021).
cancer (continued). "We hope that our findings spark a deeper investigation of TRPA1 and other TRP channels in cancer development." (PMID 34041030, 2021). "Methyl syringate (100 μM), a TRPA1 agonist, has been reported to repress hypoxia-induced cyclooxygenase-2 (COX-2) in lung A549 cancer cells." (PMID 31801263, 2019). "We therefore examined the mRNA expression of seven cannabimimetic receptors – CNR1 (CB1), CNR2 (CB2), GPR55, TRPV1, TRPV2, TRPA1, TRPM8 – and found them to be differentially expressed amongst the 12 tested cancer cell lines." (PMID 31289609, 2019). "In particular, three out of the selected ‘prostate-associated’ channels are overexpressed in PCa ECs and have marked effects on the main EC properties including proliferation (TRPV2), TEC-mediated crosstalk with cancer cells (TRPC3) and angiogenesis (TRPA1)." (PMID 31288452, 2019). "Regarding agonists or antagonists of TRPM8 channels, several are now considered in cancer prevention and therapy, although some of those reported in the literature lack selectivity for TRPM8 because they also act on TRPV1 and TRPA1." (PMID 31801263, 2019). "Thus, we hypothesized that astrocytes may be responsible for TRPA1 depletion in cancer cells possibly through intercellular communication as reported with the tumor suppressor protein, phosphatase and tensin homolog deleted on chromosome 10 (PTEN), in breast cancer." (PMID 29038531, 2017). "Conversely, CAF2 and CAF5 dominate the TME of non-responders and we were able to observe GSN negative and TRPA1 expressing stromal cells adjacent to EAC cancer cells in human specimens." (PMID 40640495, 2025). "Additionally, it explores the involvement of TRPML1, TRPA1, TRPM2, and TRPV1 in modulating reactive oxygen species (ROS) levels within cancer cells, analyzing the ROS dual role in tumor modulation." (PMID 40813985, 2025). "In summary, TRPA1 senses reactive compounds such as H2O2 and acts as a cancer pain modulator." (PMID 39273183, 2024). "Although the studies are substantial and foresee TRPA1 as a putative therapeutic target in cancer, the results do not match the analysis of patient tumours." (PMID 39770499, 2024). "BCL11B positively and significantly correlated with TRPA1 in CHOL, GBM, KICH and PRAD cancers." (PMID 39770499, 2024). "Early studies showed that AITC can induce intracellular Ca2+ signals that are not supported by TRPA1-mediated Ca2+ entry but require cytosolic ROS production in several cancer cell lines." (PMID 37443764, 2023). "TRPA1 is the most highly redox-sensitive TRP isoform and therefore its ability to mediate Ca2+ entry translates the high oxidative stress of the tumor microenvironment in an intracellular Ca2+ signal that can dramatically impact cancer cell fate." (PMID 37174661, 2023). "In addition, ectopic expression of TRPA1 rescued cell survival and prevented apoptosis in H2O2-treated TRPA1-low-expressing cancer cells." (PMID 37174661, 2023). "Emerging evidence indicates that the Ca2+-permeable, non-selective cation channel TRPA1 is upregulated in cancer cells." (PMID 37174661, 2023). "Gain variations were observed in the great majority of cancers for TRPV6, TRPV5, TRPA1, and TRPC1." (PMID 35831825, 2022). "In many cancers, including PDAC, TRPA1 stimulates tolerance to oxidative stress." (PMID 36012311, 2022). "Moreover, we also revealed several tissue or group-enriched genes (such as TRPM8, TRPA1, and TRPM3) in cancer." (PMID 35614079, 2022). "In particular, endothelial expression of TRPA1 was observed in tumor areas in all patient tissues (n = 10/10), with negative staining on cancer cells in 8 out of 10 patient samples (Figure 2aaii)." (PMID 31288452, 2019). "On the other hand, in GBM cells, it has been shown that inhibition of TRPA1 is not a good strategy to kill cancer cells." (PMID 31801263, 2019). "This implies that under an acidic microenvironment of cancer tissues, TRPV1 may play a more critical role than TRPA1." (PMID 20422007, 2010).